MTOR (mechanistic target of rapamycin kinase)
Diseases named in the same sentence as MTOR in open-access papers (continued):
Sharing a sentence is not in itself a finding about the gene and the disease.
cervical carcinoma (continued). "As oncologic patients undergoing palliative care are reported to prefer oral treatment over intravenous application, repurposing well-established mTOR inhibitors and anti-endocrine agents for advanced cervical cancer could prove particularly beneficial." (PMID 37623437, 2023). "However, patients with advanced cervical cancer often resist cisplatin, a resistance attributed to the activation of the Akt/mTOR signalling pathway." (PMID 37836581, 2023). "As this is the first report on the mTOR pathway and ER intertwinement in cervical cancer, our findings may thereby offer interesting hypotheses for further validation." (PMID 37623437, 2023). "In conclusion, the occurrence of significant ferroptosis in cervical cancer cells may be mediated via suppression of mTOR pathway after DHODH inhibition and cisplatin combination treatment." (PMID 36672495, 2023). "Evidence on the therapeutic efficacy of mTOR inhibition in recurrent cervical cancer patients is limited but appears to have the potential to temporarily halt disease progression, even in heavily pretreated stages, while inducing only mild to moderate side effects." (PMID 37623437, 2023). "The reactivation of Akt-mTOR by caAkt1 suppressed SLC5A3 KO-induced cervical cancer cell death." (PMID 37324953, 2023). "Moreover, the combination of DHODH inhibition and cisplatin synergistically inhibits the growth of cervical cancer cells in vitro and in vivo by ferroptosis via the mTOR pathway." (PMID 36672495, 2023). "As therapeutic alternatives for recurrent cervical cancer patients are limited, further evaluation of combined mTOR and ER targeting in selected cervical cancer patients could appear promising to improve palliative care." (PMID 37623437, 2023). "Thus, Akt-mTOR inhibition is another important mechanism of SKI-V-induced anti-cervical cancer activity." (PMID 35541904, 2022). "Furthermore, the study asserted the necessity of in-depth investigations on the PI3K/Akt/mTOR axis to develop more specifically targeted patient-tailored treatments in cervical cancer." (PMID 36354662, 2022). "Additionally, another recent study has shown that the LINC00861/miR-513b-5p axis inhibits cancer cell progression through the PTEN/AKT/mTOR signaling pathway in cervical cancer cells." (PMID 36146599, 2022). "It was also discovered that PD may limit cervical cancer HeLa cell proliferation and induce apoptosis, and the process could be linked to blockage of the PI3K/AKT/mTOR signaling pathway and gene downstream expression." (PMID 36364001, 2022). "Indeed, it has been reported that inactivation of mTOR increased the sensitivity of cells to paclitaxel in cervical cancer cells." (PMID 36289850, 2022). "They demonstrated that inhibition of miR-338 expression could decrease p-mTOR and p-p70S6 expression, suggesting that miR-338 decreases autophagy in cervical cancer cells by activating the mTor signaling pathway." (PMID 35456001, 2022). "Further research focused on the PI3K/Akt/mTOR axis and selective therapeutic approaches targeting this pathway could help develop better targeted therapy strategies for cervical cancer." (PMID 36354662, 2022). "Moreover, SKI-V inhibited Akt-mTOR (mammalian target of rapamycin) activation in primary cervical cancer cells, and its cytotoxicity was mitigated by a constitutively-active Akt." (PMID 35541904, 2022). "Thus Gαi3 silencing-induced anti-cervical cancer cell activity was possibly due to inactivating Akt-mTOR activation." (PMID 36263185, 2022). "The PI3K-Akt-mTOR cascade could be a valuable and promising therapeutic target and the biomarker predicting the prognosis of cervical cancer 63-65." (PMID 35541904, 2022).
cervical carcinoma (continued). "Moreover, Gαi3 overexpression-induced proliferation and migration acceleration was largely inhibited by LY294002, the PI3K-Akt-mTOR inhibitor, in cervical cancer cells." (PMID 36263185, 2022). "Therefore, TN indeed induced degradation of EGFR and PDGFRα and suppressed PI3K/Akt/mTOR cascade in cervical cancer cells." (PMID 39282148, 2022). "Adrenergic receptor proteins alpha 2a (Adra2a) inhibits the activation of PI3K/Akt/mTOR pathway in cervical cancer cells which suggests that there could be a direct relation between adrenergic receptor protein functions and Fib-3." (PMID 35795376, 2022). "Moreover, PI3K-Akt-mTOR cascade is essential for the virus/host cell crosstalk in HPV-positive cervical cancer." (PMID 35541904, 2022). "Interestingly, reduced expression of miR-338 directly led to increased autophagy in cervical cancer cells, which was similar to the mTOR signaling inhibitor rapamycin." (PMID 35456001, 2022). "The results indicate that miR-338 may inhibit cell proliferation and autophagy by targeting the mTOR signaling pathway via ATF2 in cervical cancer cells." (PMID 35456001, 2022). "Relevant research showed, trametinib combined with PI3K/mTOR dual inhibitor dactylitis can eliminate the enhancement of nuclear receptor related-1 protein (Nurr1) to cervical cancer cell aggressiveness by upregulating p21 and p27 expression and inhibiting MMP9 and KLF4 expression." (PMID 36204323, 2022). "Indeed, the PIK3CA gene is described as the top altered gene in cervical carcinoma along with the MTOR, KMT2D and FAT1 genes." (PMID 36010253, 2022). "Here we found that Gαi3 is vital for Akt-mTOR cascade activation in cervical cancer cells." (PMID 36263185, 2022). "Additionally, baicalein-mediated inactivation of the AKT/mTOR pathway has also been demonstrated in cervical cancer cells." (PMID 35955525, 2022). "ATF2 was also identified as a target gene of miR-338-3p, and it could inhibit the proliferation of cervical cancer cells via targeting the PI3K/Akt/mTOR signaling cascade." (PMID 35765408, 2022). "Meanwhile, the PI3K/AKT/mTOR signaling pathway was a vital regulatory pathway in cervical cancer." (PMID 36408157, 2022). "One study has revealed increased expression of mTOR in cervical cancer." (PMID 35477450, 2022). "The effects of CD155 on cervical cancer progression involve mechanisms other than AKT/mTOR/NF-κB." (PMID 34164340, 2021). "However, only limited evidences supported the correlation of PIK3CA alterations with the response to the mTOR inhibitors in cervical carcinoma." (PMID 35071000, 2021). "•LDN mediated the propagation property in cervical cancer through PI3K/AKT/mTOR signaling pathway." (PMID 33540155, 2021). "However, the exact role of the PI3K/AKT/mTOR activation in RCC1-induced cervical cancer development is still unclear." (PMID 34356619, 2021). "Moreover, RCC1 S11 was phosphorylated by the PI3K/AKT/mTOR pathway in HPV-positive cervical cancer SiHa and HeLa cells." (PMID 34356619, 2021). "In conclusion, notoginsenoside R7 could be used for the treatment of cervical cancer and other PI3K/PTEN/Akt/mTOR signaling-associated tumors." (PMID 33466408, 2021). "Thus, the PI3K/AKT/mTOR pathway is an extremely complicated intracellular network, but the precise role of the PI3K/AKT/mTOR pathway in cervical cancer is still uncertain." (PMID 34356619, 2021). "Another therapeutic opportunity could be to reduce long non-coding RNA oncogenes such as gastric carcinoma proliferation enhancing transcript 1 (GHET1), which has been shown to activate both mTOR and Wnt/β-catenin pathways in cervical cancer." (PMID 33668092, 2021). "In conclusion, Isoflurane enhanced proliferation of cervical cancer cells through upregulation of histone deacetylase 6, which was associated with mTOR-dependent pathway, but not AKT-mediated pathway." (PMID 32833118, 2021). "Activation of the mTOR signaling pathway has been observed in cervical cancer." (PMID 34659408, 2021).
cervical carcinoma (continued). "It was reported that BNIP1 could restrain cervical cancer cell proliferation, migration and invasion by inhibit mTOR signaling pathway, although it seemed to be a risky factor in UM patients." (PMID 33682883, 2021). "Our findings indicate that activation of mTOR pathway might be an explanation for the isoflurane-induced expression of HDAC6 in cervical cancer cells." (PMID 32833118, 2021). "We revealed that DIAPH3 promoted proliferation through mTOR signaling pathway in cervical cancer." (PMID 34659408, 2021). "Moreover, baicalein inactivated the AKT/mammalian target of rapamycin (mTOR) pathway by targeting the circHIAT1/miR-19a-3p axis to inhibit the proliferation of cervical cancer cells." (PMID 34680171, 2021). "However, in the present study, we observed that isoflurane increased p-AKT and p-mTOR expression in cervical cancer cells." (PMID 32833118, 2021). "TRIM28 also affected the mTOR signaling pathway, resulting in the growth of cervical cancer." (PMID 34722282, 2021). "Additionally, it has been well recognized that the PI3 kinase/Akt/mTOR signaling pathway plays a pivotal role in development of cervical cancer and inhibition of mTOR kinase activity suppress tumor development." (PMID 33990639, 2021). "Combined with the inhibitory effect of baicalein on cervical cancer HeLa cells proliferation, it is inferred that the mTOR/p70S6K signal pathway might involve in the inhibitory effect of baicalein on proliferation of cervical cancer cells." (PMID 33777154, 2021). "Importantly, therapy targeting the mTOR signaling pathway indicates clinical benefits in cervical cancer." (PMID 34659408, 2021). "The results revealed that protein levels in tumor tissue were higher after treatment with histamine, indicating that the treatment with histamine suppressed cell apoptosis via the PI3K/Akt/mTOR pathway, which leads to the positive influence of histamine on cervical cancer development." (PMID 32340124, 2020). "In this study, we found that ARCSP induced the accumulation of nonfused autophagosomes by activating the AMPK/mTOR pathway, inhibiting proliferation and causing cytotoxic death of cervical cancer cells." (PMID 32962728, 2020). "Furthermore, melittin showed anticancer and antiangiogenic effects by suppressing expression of hypoxia-inducible factor-1α (HIF-1α) and vascular endothelial growth factor (VEGF) through inhibition of ERK and mTOR pathways in human cervical cancer cells." (PMID 30866426, 2019). "Furthermore, they have also been reported to negatively regulate several EMT inducers, such as Notch, c-Myc and mTOR, particularly in gastric and cervical cancer." (PMID 31906201, 2019). "Hence, the PI3K/AKT/mTOR axis is considered to represent a promising therapeutic target also for the treatment of cervical cancer for which the current standard therapy consists of surgery together with radiotherapy or cisplatin-based chemoradiation." (PMID 31058807, 2019). "As for autophagy, BCL2L10 could bind to BECN1 that was an inducer of autophagy at BH1 or BH3 domain, reducing autophagic cell death in cervical cancer by mTor signaling pathway." (PMID 30696802, 2019). "Additionally, metformin can suppresses PI3K/Akt/mTOR signal pathway and has been presented to have chemopreventive activities against cervical cancer." (PMID 31870092, 2019). "Furthermore, we observed that combination treatment with RAME and cisplatin greatly enhanced the anti-tumor effect in cisplatin-resistant cervical cancer cells, which was likely due to mTOR/S6K1 inhibition-mediated autophagy and apoptosis." (PMID 31387554, 2019). "Considering the reported alternations in PI3K/mTOR/Akt pathway in cervical cancer, mTOR inhibitors may play a vital role in treatment." (PMID 29434241, 2018).
cervical carcinoma (continued). "In cervical cancer, the association between HPV infection and dysregulation of phosphoinositide 3-kinase (PI3K)/protein kinase B (AKT)/mammalian target of rapamycin (mTOR) pathway (PI3K/AKT/mTOR pathway) places mTOR as an attractive therapeutic target." (PMID 29434241, 2018). "Importantly, the mTOR pathway is strongly repressed under hypoxia in many cell systems, including cervical cancer cells." (PMID 28678198, 2017). "Initially, to test if the inhibitory activity of Zey on cervical carcinoma cells was associated with abrogation of PI3K/AKT/mTOR pathways, phosphorylation of PI3K, and corresponding signals AKT, mTOR, and P70S6K were detected by western blot analysis after cells were exposed to Zey for 24 h." (PMID 28490807, 2017). "Our findings demonstrate for the first time that R7 induces apoptosis through PI3K/PTEN/Akt/mTOR inhibition, and may be a promising candidate in the clinical treatment of cervix cancer." (PMID 29312623, 2017). "Altogether, these results revealed that the mTOR pathway may interact with PKM2 to modulate cisplatin sensitivity in cervical cancer." (PMID 27492148, 2016). "LA induced autophagy via PI3K/Akt/mTOR signaling which repressed cervical cancer growth." (PMID 26999089, 2016). "Abnormal activation of mTOR signaling occurs in various human cancers, including cervical cancer." (PMID 27517315, 2016). "Whether PKM2 expression predicts cisplatin-based NACT sensitivity and is mTOR dependent in cervical cancer patients remains unclear." (PMID 27492148, 2016). "Therefore, we postulated that mTOR pathway was involved in PKM2 modulated cisplatin sensitivity in cervical cancers." (PMID 27492148, 2016). "Thus, our findings update the signal transduction pathways of PGRN by suggesting that mTOR signaling contributes to PGRN-stimulated carcinogenesis of cervical cancer." (PMID 27517315, 2016). "The PGRN/PI3K/Akt/mTOR signaling pathway may be a novel candidate for targeted therapy in PGRN-associated malignancies, including cervical cancer." (PMID 27517315, 2016). "Moreover, we established PKM2 suppressed cervical cancer cell lines and evaluated their sensitivity to cisplatin and interaction with mTOR pathway." (PMID 27492148, 2016). "To investigate whether TNFRs are needed for PGRN-mediated mTOR signaling, we detected the phosphorylation of mTOR and p70S6K in cervical cancer cells with reduced expression of TNFR1 or/and TNFR2 after rhPGRN treatment." (PMID 27517315, 2016). "Interestingly, Fx has been shown to induce apoptosis in human cervical cancer HeLa cells through inhibition of the PI3K/Akt/mTOR pathway." (PMID 26264004, 2015). "Activated PI3K/AKT/mTOR pathway frequently occurs in metastatic or recurrent cervical carcinomas." (PMID 25426553, 2014). "mTOR signaling pathway inhibitors might be a new therapeutic treatment in cervical cancer, and SPAG5 expression in cervical cancer may be a potential indicator for mTOR inhibitor treatment." (PMID 24853425, 2014). "In this study, we hypothesized that cisplatin treatment administered together with genistein could potentiate cervical cancer growth inhibition in vitro through downregulation of mTOR pathway." (PMID 23056046, 2012). "Therefore, it was hypothesized that RACK1 may activate AKT/mTOR signaling by interacting with AKT in cervical cancer cells." (PMID 39425259, 2025). "In addition, RBM15-mediated m6A modification facilitated the expression of the oncogene Otubain 2 (OTUB2) in cervical cancer cells, which further activated AKT/mTOR signaling, thereby promoting the proliferation, migration, and invasion of cervical cancer cells." (PMID 38915367, 2024).
cervical carcinoma (continued). "Early studies assessing mTOR inhibitor efficacy in heavily pretreated cervical cancer patients observed low objective response rates yet notably high rates of temporary disease control in up to 60% of patients with incurable disease, while mTOR inhibition appears relatively safe and well tolerated." (PMID 37623437, 2023). "Moreover, inhibiting DHODH in cervical cancer cells both in vitro and in vivo produced a synergistic anticancer effect with cisplatin, which may be achieved by mTOR pathway suppression." (PMID 36672495, 2023). "Therefore, the combination of DHODH inhibition and cisplatin exhibits synergistic effects on ferroptosis induction via inhibiting the mTOR pathway could provide a promising way for cervical cancer therapy." (PMID 36672495, 2023). "BAI inhibits cell proliferation via blocking of the mTOR/p70S6K pathway and suppresses EMT pathway-associated migration through the TGFβ pathway in cervical cancer HeLa cells; however, the effect on the mechanism of BAI on RA development and progression still remained unknown." (PMID 36118088, 2022). "Moreover, licochalcone A (LicA), another flavonoid extracted from Glycyrrhiza inflata Batalin root, has been shown to induce cell death and autophagy in cervical cancer cells by downregulation of the phosphatidylinositol 3-kinase (PI3K)/Akt/mammalian target of the mTOR signaling pathway." (PMID 36428613, 2022). "Interestingly, CD38 activates the PI3K/AKT/mTOR signaling in cervical cancer cells." (PMID 36490326, 2022). "It has been reported that dysregulation of various oncogenic proteins, including E6/E7/E5 overexpression, could induce Akt-mTOR signaling hyperactivation to promote cervical cancer progression; it would be interesting to further explore the potential effect of TN on these oncogenic proteins." (PMID 39282148, 2022). "In addition, overexpression of miR-202-5p suppressed the expression of PIK3CA and inhibited the activation of PI3K/Akt/mTOR signaling pathway, suppressing proliferation and the progression of epithelial-mesenchymal transition as well as the invasion of cervical cancer." (PMID 35682549, 2022). "Additionally, lncRNA GHET1 could accelerate the development of cervical cancer via modulating the AKT/mTOR and Wnt/β-catenin signaling pathways." (PMID 34372865, 2021). "Notably, the expression of mTOR was increased in Msi1-overexpressing cells but decreased in siMsi1-modified cells, suggesting another possible mechanism by which Msi1 promotes the proliferation of cervical cancer cells." (PMID 33758618, 2021). "In addition, Msi1 increased the expression of mTOR, suggesting that Msi1 accelerated the proliferation of cervical cancer cells might not only through regulating the cell cycle, but also modulating the AKT signaling." (PMID 33758618, 2021). "Thus, it indicated the knockdown of WASL might be correlated with biological processes such as glycolysis, TNFα signaling, mTOR signaling, and Wnt/β-catenin signaling, which, in return, might suppress the progress of cervical cancer in clinical settings." (PMID 34222242, 2021). "Therefore, luteoloside might be a promising candidate agent against cervical cancer targeting for mTOR." (PMID 29874795, 2018). "Inhibition of PGRN/PI3K/Akt/mTOR signaling may be targeted in treatment of cervical cancer." (PMID 27517315, 2016).